GAPDH (glyceraldehyde-3-phosphate dehydrogenase)
Diseases named in the same sentence as GAPDH in open-access papers (continued):
Sharing a sentence is not in itself a finding about the gene and the disease.
tumor (continued). "The combination of inhibitors of GAPDH and oxidative phosphorylation significantly suppresses cell proliferation in vitro and tumor growth in vivo." (PMID 31324208, 2019). "Another way through which cytosolic GAPDH is involved in tumor survival is the escape from caspase-independent cell death (CICD)." (PMID 31027346, 2019). "For the quantitative PCR, we used human GAPDH, a highly expressed molecule typically used as the housekeeping gene to evaluate the number of human tumour cells." (PMID 31331338, 2019). "The growth profile of the tumor was simulated to mimic time-based partial inhibition (90%) of three reactions—GAPDH, OXPHOS and ASCT2." (PMID 31185009, 2019). "The expression levels of the SLC1A1 and GAPDH genes were measured in tumor and formalin-fixed paraffin-embedded (FFPE) tissue specimens from the adjacent healthy kidney of each subject." (PMID 30862152, 2019). "This study is the first to report the demonstration of a possible mechanism achieved through targeting the GAPDH enzyme, which produced a very significant anti-tumor response." (PMID 31612140, 2019). "Overexpression of GAPDH is positively correlated with tumor progression in many cancers and its depletion is reported to induce premature senescence in tumor cells." (PMID 30700763, 2019). "Combination index analysis and xenograft animal model were conducted to explore the effects of combination of inhibitors of glyceraldehyde-3-phosphate dehydrogenase (GAPDH) and oxidative phosphorylation on tumor growth." (PMID 31324208, 2019). "As an effective inhibitor of glycolytic enzymes, especially for HK-II and GAPDH overexpressed in most tumor cells, in this case, we can keep in mind that 3-BrPA can selectively target tumor cells characterized by a high glycolytic phenotype." (PMID 30845728, 2019). "We also examined the relative expression of CTD-2547G23.4 in 39 pairs of HCC tissues matched with adjacent non-tumour tissues by qRT-PCR analysis normalized to GAPDH." (PMID 29780284, 2018). "mRNA levels in each cancer cell line and tumor tissue were normalized to the relative quantity of GAPDH expression and then adjusted to the express levels in 293 T cells (set as 1)." (PMID 29625565, 2018). "We performed qRT-PCR to measure SFTA1P expression in 68 pairs of human GC tissues and corresponding non-tumor normal tissue (all normalized to GAPDH expression)." (PMID 29523596, 2018). "Further, we observed that most bone marrow samples from PC3 or C4-2B tumor-burden mice were detected human GAPDH expression." (PMID 29507684, 2018). "A recent study overcomes hypoxia-induced tumor cell resistance by synergistic GAPDH-siRNA and chemotherapy, indicating the important roles of GAPDH in tumor cell resistance." (PMID 29915691, 2018). "The expression level of each gene was normalized to GAPDH expression and adjusted to the levels in vector-transfected tumor cells." (PMID 29625565, 2018). "Upon the completion of the experiment, mice were sacrificed and tumor specimens were used to examine the protein level of survivin gene while using GAPDH as internal control." (PMID 30279553, 2018). "GAPDH was selected as a reference gene as GAPDH levels had minimal variability in expression between normal and tumor tissues and between tumor subgroups with the majority of Ct values between 20 and 22 cycles." (PMID 29888503, 2018). "On the contrary, two bands, specific for both, FAM107A and GAPDH genes were visible in all applied non-tumor controls (9/9)." (PMID 28710449, 2017). "In contrast, it was reported that GAPDH translocates to the mitochondria of cerebellar granule cells and several tumor cell lines during apoptotic stimulation, such as with serum deprivation or treatments with staurosporine, etoposide, and lonidamine." (PMID 28167533, 2017). "linc00261 expression was also significantly lower in tumour tissues than in adjacent normal tissues (n = 80, P < 0.01), as determined with qRT‐PCR and normalized to GAPDH." (PMID 27878953, 2017).
tumor (continued). "Tumour cells were immunopositive for glyceraldehyde-3-phosphate dehydrogenase, enolase and recoverin as well as neuroendocrine markers." (PMID 28382556, 2017). "To investigate the role of PVT1 in ESCC progression, we detected the PVT1 expression levels in 104 paired ESCC cancer tissues and corresponding non-tumor tissues using qPCR, which was normalized to GAPDH." (PMID 28404954, 2017). "We immunoprecipitated GAPDH in normal and 3MC induced tumor tissue lysates using antibody against GAPDH, and the precipitate was further probed with antibodies against PKM2, GPI, and GAPDH." (PMID 26911935, 2016). "All these data were normalized by the contents of GAPDH, an endogenous reference mRNA widely used for its stable expression in tumor tissue." (PMID 27673330, 2016). "The reduction of GAPDH can prevent the entry into S phase of the cell cycle and arrest cell cycle in the G0/G1 phase, thereby inhibiting tumor cell proliferation." (PMID 27293463, 2016). "In contrast, GAPDH activity was reduced to 26.8 ± 5 % in the 3MC induced tumor tissue and to 57.8 ± 2 % in EAC cell lysates of total activity in the presence of 1 mM MG." (PMID 26911935, 2016). "The detected differences of GAPDH, β-F1-ATP-ase expression and adenylate energy charge in HT-1080 and ZR-75.1 tumour cells also confirmed the altered metabolism." (PMID 26869854, 2016). "In this paper we demonstrate that association of GAPDH with GPI or PKM2 exists in both EAC cells and 3MC induced tumor tissue." (PMID 26911935, 2016). "Altogether these data suggest that tumor cells show increased expression of PKM2 and GPI, and two types of GAPDH association-one is GAPDH-GPI and another is GAPDH-PKM2-exist in the 3MC induced tumor tissue." (PMID 26911935, 2016). "This therapeutically exciting difference has been attributed to alterations in complex I and GAPDH of tumor cells that increase sensitive to methylglyoxal with respect to non-tumor enzymes." (PMID 27721794, 2016). "RT-qPCR was subsequently repeated for five promising targets, in addition to E-cadherin (CDH1) for all the 15 patient tumor samples and four dura controls, using three reference genes (GAPDH, ACTB (β-Actin) and HPRT)." (PMID 26950155, 2016). "We found that both PKM2 and GPI were increased whereas GAPDH was reduced in the tumor (lane 3 and 4) compared with the normal tissue (lane 1 and 2)." (PMID 26911935, 2016). "First, we examined the lncRNA TUSC7 expression level in 75 paired HCC tissues and adjacent non-tumor tissues by qRT-PCR and normalized them to GAPDH." (PMID 27002617, 2016). "In this study, treated with Brucea javanica oil the level of GAPDH and Akt in tumor tissue decreased." (PMID 26508976, 2015). "GAPDH is a key enzyme in glycolysis which provide the energy for tumor cells under hypoxia condition." (PMID 25691059, 2015). "Within all tumor samples, enFeLV RNA copies per 1.00 × 106 copies of GAPDH were found to be lower in comparison to the control samples." (PMID 25879730, 2015). "Although the upregulation of Tom20 compared to upregulation of GAPDH was greatest near the rim, Tom20 upregulation was still significantly higher than GAPDH deeper (>1 mm) into the tumor, although only by <10%." (PMID 26032618, 2015). "Relative Elf5 levels in tumor tissue from 50 UC patients were determined by qRT-PCR spanning 90 bp, normalized by GAPDH, and were compared with the median of 10 normal tissue control samples." (PMID 25629735, 2015). "The expression of Dppa4 in tumor tissue was examined and compared with paired normal colonic mucosa in 39 patient samples using real-time PCR with GAPDH as the internal reference." (PMID 26063247, 2015). "Even deeper into the tumor (2.0–2.5 mm) the mean increase in Tom20 labeling was statistically greater that of GAPDH, the mean ratio over 2.0–2.5 mm being 1.084 (SEM." (PMID 26032618, 2015).
tumor (continued). "Confirmation of these findings was done by RT-qPCR, where similar values were obtained: the mean enFeLV copies per 1.00x106 GAPDH for all tumor samples turned out to be 4.60-fold lower compared to the mean value of the control samples." (PMID 25879730, 2015). "In the following analyses, MACC1 expression, normalized to GAPDH expression, in tumor tissue was calculated following division by MACC1/GAPDH expression in the normal tissue." (PMID 25295116, 2014). "Considering groups based on tumor stage the average expression of all genes except for GAPDH was substantially stable." (PMID 25473950, 2014). "We were able to identify human GAPDH mRNA in ELMs of blood and saliva of tumor bearing mice using nested RT-qPCR." (PMID 25397880, 2014). "Differently, expression of all genes except for GAPDH shows to remain stable among tumor stages, but the extreme imbalance in the number of patients per group has to be considered in the evaluation of those results." (PMID 25473950, 2014). "40% and 33% of all tumor-bearing mice carried the human GAPDH mRNA in their blood and salivary ELMs respectively." (PMID 25397880, 2014). "In our study, COX-2 mRNA tumor/normal ratios normalized with respect to GAPDH showed the lowest correlation compared with normalization for tissue weight." (PMID 24383454, 2014). "We were able to identify hCD63-GFP positive ELMs and human GAPDH mRNA in hCD63 positive ELMs in the blood and saliva of tumor bearing mice." (PMID 25397880, 2014). "In the following analyses, ANXA9 expression normalized by GAPDH expression in the tumor tissue was calculated following division by ANXA9 expression level in the normal tissue." (PMID 25289111, 2014). "MACC1 expression was calculated by normalising it to GAPDH expression for each tumor or normal tissue sample." (PMID 25295116, 2014). "Regardless of HCC stages, HBx expression level normalized with GAPDH was about 3 fold higher in tumor tissues than in non-tumor tissues (*** p<0.005; Wilcoxon's signed-rank test)." (PMID 25361011, 2014). "The candidate reference genes identified as being the most suitable for normalization under the current experimental conditions were GTP-binding protein, translationally controlled tumour protein and glyceraldehyde-3-phosphate dehydrogenase." (PMID 24790133, 2014). "When normalized with respect to the housekeeping genes B2M or GAPDH, mean tumor/normal ratios were 16.1 and 7.5, respectively." (PMID 24383454, 2014). "Using GAPDH as an internal control, the ratio of the candidate gene transcript between the tumor and the matched normal tissues [tumor/normal (T/N)] was calculated." (PMID 24137407, 2013). "We next immunoblotted for glyceraldehyde-3-phosphate dehydrogenase (GAPDH) because tumor cells have altered metabolism and sirtuins can influence metabolic and energetic regulation." (PMID 24259290, 2013). "An alternative promising therapeutic approach to date in terms of inhibiting tumor glycolysis has been targeting the enzyme GAPDH." (PMID 24298908, 2013). "In this retrospective study, we measured GAPDH gene expression, by RQ-PCR, on tumor samples from a group 82 resected NSCLC patients." (PMID 23988223, 2013). "We have identified a group of genes for which mRNA expression strongly correlates with GAPDH expression in tumor cells." (PMID 23620736, 2013). "Using quantitative PCR techniques, we determined the relative content of mtDNA with respect to the GAPDH gene in 124 OSCC patients with different tumour stage and in the normal oral mucosal cells in 140 individuals without disease." (PMID 23469236, 2013). "Eighteen patients had a tumor GAPDH mRNA expression of less than 0.25, and 37 cases expressed at least 0.25 relative to reference genes and positive control." (PMID 24252137, 2013). "Current advancement in understanding the cancer-related roles of GAPDH together with the sensitivity of tumor cells to its inhibition designates GAPDH as a potential molecular target in cancer treatment." (PMID 22964488, 2012).
tumor (continued). "In summary, molecular targeting of GAPDH via percutaneous injection of either an inhibitor, 3-BrPA, or shRNA blocks tumor progression demonstrating the therapeutic potential of targeting GAPDH in HCC." (PMID 22964488, 2012). "The CEA, CK19, CK20 and CD133 mRNA levels were normalized with GAPDH mRNA levels in the portal system blood samples from 20 patients with benign diseases prepared for the control of tumor drainage blood to determine the cut-off levels." (PMID 22267181, 2012). "By qPCR, significantly higher FRα mRNA was found in cancer samples when compared with the corresponding non-tumor counterparts after normalization with GAPDH (P = 0.015)." (PMID 23144806, 2012). "The tumor specific roles of GAPDH include, apart from its glycolytic function, chemoresistance, metastatic potential, protecting cells against caspase-independent apoptosis and cell cycle regulation." (PMID 22964488, 2012). "Although very interesting, additional experimental evidence validating the tumor selectivity and molecular specificity (showing GAPDH as the only or at least the primary target) of MG in multiple tumor models will help further advancement of MG." (PMID 22964488, 2012). "This visual observation was even more prominent when we performed quantification of metastatic burden by qRT-PCR of human glyceraldehyde-3-phosphate dehydrogenase (GAPDH) as a marker of the human tumor cells." (PMID 21541352, 2011). "Two specific human GE Array Kits (Superarray Inc.)that both contain 23 marker genes, related to signal transduction pathways or cancer/tumor suppression, plus 2 housekeeping genes (β-actin and GAPDH), were utilized." (PMID 20953429, 2011). "In normality test, ACTB, HPRT1, and 18S rRNA in 'normal stomach tissues' group and all genes except for GAPDH in 'tumor stomach tissues' followed normal distribution by KS-test." (PMID 20507635, 2010). "This suggests that GAPDH expression in tumor stomach tissues are highly elevated compared to the other reference genes." (PMID 20507635, 2010). "ACTB and GUSB selection, based on geNorm analysis including the seven potential housekeeping genes, probably resulted from similarities in the expression pattern of these two genes, which are both significantly up regulated in tumor tissues, as well as GAPDH." (PMID 19257903, 2009). "β-globin mass signals showed a significantly decreased intensity in tumor samples when compared with normal lung ones, while GAPDH and β-actin peaks showed increased intensity in tumor samples." (PMID 19890392, 2009). "Transcript levels were further analyzed by TaqMan qRT-PCR, with the glyceraldehyde-3-phosphate dehydrogenase gene (GAPDH) as the endogenous control gene and the average level of colon tumor samples as reference." (PMID 21637440, 2009). "The high-expression group comprised patients who had a level of TRIB3 expression higher than the median value for TRIB3/GAPDH expression in tumour regions compared with normal regions (n=101); other patients were assigned to the low-expression group (n=101)." (PMID 19904274, 2009). "Overview of GAPDH expression in different tumor and non-tumor cell lines as a consequence of the development of a hypoxic cellular microenvironment." (PMID 19144146, 2009). "Analysis for 11 potential endogenous controls in a random selection of 14 (seven tumour; seven normal) specimens indicated 18S, β2-microglobin, β-actin and GAPDH mRNAs to be expressed at similar levels in all specimens analysed." (PMID 18475297, 2008). "The mean expression value of MCAK mRNA in tumour samples, 0.53±0.037 (mean±s.d., normalised by GAPDH gene expression), was significantly higher than the value, 0.32±0.037, for the corresponding normal samples (P<0.01; Student's t-test)." (PMID 18506187, 2008). "We next quantified the GPR30 mRNA levels relative to the GAPDH levels in normal tissues and their matched tumor tissues using RT quantitative real-time PCR and comparative delta Ct method." (PMID 21655374, 2008).
tumor (continued). "CLDN1 mRNA was downregulated by 12-fold in the sample (tumour) group as compared with the control group using GAPDH as the reference gene." (PMID 15743508, 2005). "CLDN1 was downregulated by 12-fold in the sample (tumour) group in comparison with the control group using GAPDH as the reference gene." (PMID 15743508, 2005). "Under the assumption that the efficiency of reverse transcription was constant, the induction ratio of mRNA of p16 (tumour vs normal tissue) is estimated 162.2 after compensation for GAPDH induction." (PMID 15292938, 2004). "The standard curve with a correlation coefficient of 0.99 was used for a relative quantification of the copy numbers obtained from XIAP, Smac/DIABLO and GAPDH in each tumour sample." (PMID 15328523, 2004). "From the formula described in Materials and methods, cDNA ratios of p16 (tumour vs normal tissue) and GAPDH were 1371 and 8.456." (PMID 15292938, 2004). "Relative mRNA levels of target genes were normalised to GAPDH and β-actin, and Tumour/Normal (T/N) ratios were calculated." (PMID 12087473, 2002). "The survivin/GAPDH ratio of 16 tumours with strong survivin protein expression (11.5±2.1) was significantly higher than that of 41 tumours with weak expression (2.9±0.3, P<0.0001)." (PMID 12373603, 2002). "Moreover, the glycolytic genes HK2, GAPDH and ENO1 showed elevated expression levels in INSS stage 4 tumours when compared to stage 1 tumours, highlighting the increasing energy demands associated with cancer metastasis." (PMID 41420301, 2025). "Modifications of cysteines even distal from the active site might however impact enzymatic activity, and for both PKM2 as well as for GAPDH, protein levels were prominently increased in tumor tissue." (PMID 40461450, 2025). "Therefore, inhibiting GAPDH can play a significant role in cancer treatment, especially in treating tumor cells resistant to traditional therapy." (PMID 40076506, 2025). "Moreover, GAPDH plays a vital role in tumor cell survival, angiogenesis, and the post-transcriptional regulation of tumor cell mRNA." (PMID 39759516, 2024). "In tumour infiltrating T lymphocytes, low levels of glucose trigger binding of Glyceraldehyde-3-phosphate dehydrogenase (GAPDH) to IFNγ transcripts, this interferes with histone acetylation preventing differentiation of CD4+ T cells into the immunogenic Th1 phenotype." (PMID 39282472, 2024). "Focusing on glucose metabolism, the glycolytic metabolite phosphoenolpyruvic acid (PEP) can influence the activity of tumor-infiltrating lymphocytes (TILs), and enzymes such as glyceraldehyde-3-phosphate dehydrogenase (GAPDH) serve as metabolic checkpoint regulators." (PMID 39119332, 2024). "HA is a known GAPDH inhibitor which exhibited selective toxic effects on several tumor cells." (PMID 38512909, 2024). "Other studies have shown that GAPDH plays crucial roles in tumor cell survival, angiogenesis, the regulation of gene expression in tumor cells, and the post-transcriptional regulation of tumor cell mRNA." (PMID 38928396, 2024). "Another hypothesis is that stromal cells in the tumor tissue increased, which express GAPDH, and this masked the qPCR results when normalizing luciferin expression." (PMID 38958560, 2024). "Tumor-associated macrophages (TAMs) are known to play an important role in HCC progression, and active secretion of GAPDH by miR-4669 overexpression in Hep3B cells may generate an immunosuppressive tumor microenvironment through M2 macrophage polarization." (PMID 37175615, 2023). "Meanwhile, it was shown that a high expression of the GAPDH plays a facilitating role in the assembly and secretion of exosomes by cells, which is consistent with the TRIB3high tumor epithelial cells, and this is probably a potential mechanism for the regulation of TME of such subset." (PMID 37153569, 2023). "In summary, increased GAPDH expression predicts a suppressive tumor immune microenvironment." (PMID 36837761, 2023).